ENSG00000274760
Gene: Miscellaneous RNA gene on chromosome 20 (49,279,116 to 49,279,208, forward strand). Ensembl gene ENSG00000274760.
Gene Ontology:
Cellular component: cytoplasm; nucleus